CD69 (CD69 molecule)
Diseases named in the same sentence as CD69 in open-access papers (continued):
Sharing a sentence is not in itself a finding about the gene and the disease.
COVID-19 (continued). "Of interest, among the significant plasma cytokines detected in COVID-19 patients, IL-8 showed a positive correlation with CD19, CD69 and ROR1 whereas IL-6 positively correlates with MFI CD24." (PMID 37207201, 2023). "Genes involved in activation of memory B cells, including CD69 and ZEB3, higher in COVID-19 patients relative to healthy donors." (PMID 37848421, 2023). "A large network of cells correlating with each other was increased in COVID-19, including groups of proliferating or activated CD4, CD8, Treg, B cells, plasma cells, NK (CD69+), and cMono." (PMID 36669118, 2023). "The percentage of activated (CD69+) total ILCs and activated ILCp positively correlated with serum IL-6 levels and with CXCL10 levels in the COVID-19 patients." (PMID 35159352, 2022). "Known markers of CD4+ T cell activation (T-bet, Ki-67, CD69, TOX, and PD1) were significantly increased in baseline COVID-19 patients compared to HD." (PMID 35012610, 2022). "Adenoid tissues isolated from COVID-19 convalescents were noted to have an increased proportion of CD8+CXCR5+ T cells, additionally expressing markers CD69 and CD103 typical of tissue-resident memory cells." (PMID 36146713, 2022). "Regarding the activation state, CD69+ expression on NKT was higher in COVID-19 patients compared to HCs and non-COVID-19." (PMID 35159352, 2022). "The number of CD69+ CD8 T and CD103+CD69+ CD8 T cells in BAL was significantly increased among those post-COVID-19 patients with an FVC less than 90% of that predicted." (PMID 35151371, 2022). "The total frequency of CD8+CD69+41BB+ T cells (sum of CD8-A and CD8-B MP responses) was lower in participants with MIS-C compared with both convalescent COVID-19 (P = 0.008) and HC (P = 0.04)." (PMID 35044955, 2022). "SARS-CoV-2 spike-specific CD4+ cell responses, determined as expression of CD69+ and CD134+, were detected in all tested COVID-19 patients (n=15) and vaccinees 6 weeks (n=20), 3 months (n=15) and 6 months after the first vaccine dose (n=17)." (PMID 35529867, 2022). "A specific set of markers were evaluated in ILC; in fact, in COVID-19 patients CD56 was decreased in ILC1, while in ILC2 and ILCp was increased CD69 and only ILC2 decreased CD62L." (PMID 35159352, 2022). "In support of our findings, lymphocyte activation markers such as CD38, CD69, and CD44 are highly expressed on CD4+ and CD8+ T cells of COVID-19 patients, and CD73 absence in CD8+ T cells induces granzyme production in these individuals." (PMID 36248842, 2022). "In all patients with COVID-19, CD3+CD8+CD69+ cell counts increased compared to the control; however, the concentration of these cells in the blood reached maximum values in patients with a poor prognosis of the disease." (PMID 35632823, 2022). "Particularly in severe COVID-19 patients, higher frequencies of SARS-CoV-2-specific IFN-γ+CD69+CD4+ T cells, with a high expression of Cytotoxic T-Lymphocyte-associated Protein 4 (CTLA-4), were observed as compared to uninfected and convalescent patients." (PMID 36499533, 2022). "In this study, we found several exosomes including CD9, CD31, CD40, CD45, CD41b, CD42a, CD62P, CD69, CD81, CD105, and HLA-DRDPDQ in the plasma of COVID-19-recovered pregnant women were significantly less abundant than the control group." (PMID 35647028, 2022). "Firstly, NK cells were highly activated in COVID-19 patients and overexpressed CD25, CD69, and NKp44 on their surface." (PMID 35632823, 2022). "A positive clinical correlation was found between CD69 expression by MAIT and NKT cells in COVID-19 patients at time of admission and reduced hypoxemia after 7 days." (PMID 34050887, 2022). "CD8+ T cells have been shown to overexpress CD69 and TIM-3 in the peripheral blood of COVID-19-infected patients compared to healthy controls, which is a characteristic for a hyperactivated/exhausted T cell phenotype." (PMID 36334153, 2022).
COVID-19 (continued). "As seen with antiviral CD4+ T cells, CD8+ T cell responses (CD8+CD69+41BB+) against SARS-CoV-2 spike–containing CD8-A MP and CD8-B MP were detectable in the majority of children with convalescent COVID-19 (74% and 75% with FC > 2, respectively)." (PMID 35044955, 2022). "A report suggested that MAIT cells also expressed CXCR3, several studies have shown an increase in expression of early activation marker CD69 on MAIT cells and a decrease in expression of the homing marker CXCR3 in mild and severe cases of COVID-19." (PMID 36034704, 2022). "Subset analysis on circulating CD103+CD56+ NK cells further showed that COVID-19 patients had increased proportions of CD49d+CD103+, CD69+CD103+, and CD69+CD49d+CD103+ NK cells." (PMID 33861802, 2021). "MAIT cells from COVID-19 patients expressed significantly higher levels of the activation markers CD38, CD69 and HLA-DR, as well as of the exhaustion markers CTLA-4 and PD-1, compared to healthy controls." (PMID 33546489, 2021). "Compared to both healthy donor cohorts, we observed that more SARS-CoV-2-reactive T cells from COVID-19 patients expressed the activation markers CD38, CD39, CD69 and HLA-DR, and showed a late-differentiated effector memory profile of reduced CD27." (PMID 33853928, 2021). "The relative MFIs of CD69 and CD44 in CD4+ T cells, CD8+ T cells, and NK cells were significantly lower in RTP patients than in patients with moderate COVID-19 and severe COVID-19." (PMID 34687295, 2021). "Specifically, in the COVID-19 patient’s B cells, we detected a substantial increase in the expression of CD52, CD74, CD22 and CD79B and a decrease in CXCR4, CD69, INFGR1, PTPRC and LAMP1 transcripts with respect to control-derived B cells." (PMID 34944610, 2021). "Distinct immunotypes were evident in COVID-19 patients, with altered expression of several receptors involved in activation, adhesion, and migration of granulocytes (e.g., CD62L, CD11a/b, CD69, CD63, CXCR4)." (PMID 34548411, 2021). "We also found an increased expression of CD63, ITGB2, CD37, CD2 and IL23R markers and the reduction in CXCR4, CD69, CD48, ICAM1 and S100A10 markers in COVID-19-derived NK-T cells compared to controls." (PMID 34944610, 2021). "CD4+ T-cells in the COVID-19 group also had higher expression levels of the activation markers OX40 and CD69, as well as the chemokine receptors CCR6 and CCR4, than the other respiratory infection group, implying a stronger activation." (PMID 34835045, 2021). "Fewer CD56dimCD16brightNKG2A+NK cells and a parallel increase in the CD56+CD69+NK, CD56+PD-1+NK, CD56+NKp44+NK subset were reported in COVID-19 than HC." (PMID 34831404, 2021). "The same statistical trend toward higher CD69 frequencies was evident in the EM subset of CD8+ and CD4+ T cells in COVID-19 and malaria patients compared to healthy controls." (PMID 32983106, 2020). "CD69 was more frequently expressed on CM, TM, and EMRA CD8+ and CD4+ T cells in COVID-19 and malaria patients compared to the respective subsets of T cells in healthy individuals." (PMID 32983106, 2020). "For a description of the activation status, we assessed the frequencies of CD69 and HLA-DR/CD38 on CD8+ and CD4+ T cells in COVID-19 and malaria patients as well as in healthy controls." (PMID 32983106, 2020). "The activation markers CD69 and HLA-DR/CD38 were elevated on T cells in COVID-19 and malaria patients." (PMID 32983106, 2020). "There were increased levels of CD69 and HLA-DR/CD38 co-expression on CD8+ and CD4+ T cells in both COVID-19 and malaria patients compared to healthy controls which is characteristic for acute infections." (PMID 32983106, 2020). "Unsupervised analysis of MAIT cell flow cytometry phenotypes in all Atlas cohort patients and controls (n = 38) revealed a pattern of enhanced CD69 expression and diminished CXCR3 expression in both AM and AS COVID-19 patients." (PMID 32989174, 2020).
COVID-19 (continued). "We also observed that there was no public TCR clonotype among the different populations of Tregs and across patients with different severities of COVID-19, and there was a higher frequency of TCR sharing between HLA_DR+ Tregs and CD69+ Tregs, especially in the MR and SP groups." (PMID 40114921, 2025). "In addition, the SP group had a high suppressive score of all Tregs, CCR7+ Tregs, CD69+ Tregs, and CTLA4+ Tregs in severe COVID-19 patients." (PMID 40114921, 2025). "Notably, lower frequencies of total and CD27+ CD8+ T-cells, together with increased frequency of CD69+, CD107a+, T-bet+, and PD-1+ CD8+ T-cell subsets, were observed in COVID-19 patients progressing to death as compared to those evolving to discharge." (PMID 39597661, 2024). "Furthermore, the expression of CD142, CD49e, CD69, and CD20 on circulating EV surfaces show differences between COVID-19 (-) pneumonia and COVID-19 (+) pneumonia, and CD142 also shows differences in mild and severe cases." (PMID 39697627, 2024). "For instance, while MAIT cells are thought to contribute to anti-IAV immunity, their CD69 or HLA-DR levels have been reported to predict the severity or mortality of COVID-19 in most, but not all, studies conducted on the subject to date." (PMID 37384813, 2023). "Circulating iNKT cells, but not conventional T cells, were highly activated in COVID-19 patients (65% vs 5% CD69+)." (PMID 37566593, 2023). "CD69 and CD40L could be reliable in vitro markers for delayed hypersensitivity to COVID-19 vaccines." (PMID 37686102, 2023). "However, some studies demonstrated that these NK cells overexpressed several markers related to a dysfunctional phenotype in severe COVID-19, like CD39, PD-1, NKG2A, DUSP2, CD69, CD38, LAG-3 and TIM-3." (PMID 37311004, 2023). "Indeed, when we compared the phenotype of ILC2 present in the PBMC of HC and COVID-19 patients, we found that COVID-19 patients’ ILC2 showed a more activated phenotype characterized by an increase in CD38 and CD69 expression and a trend for increased NKG2D." (PMID 37207201, 2023). "Our study suggests CD69 and CD40L are vital in the diagnosis of COVID-19 vaccine delayed hypersensitivity and could be included in allergy work prior to vaccination." (PMID 37686102, 2023). "Six hub genes (FCGR3A, CD69, IFNG, CCR7, CCL5, and CCL4) were involved in regulating immune cells in COVID-19 and HF, which may contribute to the pathogenesis of HF." (PMID 36420258, 2022). "High expression of CD69 on CD4+ and CD8+T cells in COVID-19 leads to over-activation of NK cells and T cells, which may cause over-activation of the immune response." (PMID 36420258, 2022). "Known markers of CD8+ T cell activation (T-bet, Ki-67, CD69, TOX, and GZMB) were significantly increased in baseline COVID-19 patients compared to HD, supporting our hypothesis that SARS-CoV-2 infection increases peripheral T cell activation." (PMID 35012610, 2022). "Many of these cells were bystander (non-SARS-CoV-2-specific) CXCR4+ CD69+ T cells whose numbers in blood increased prior to death from COVID-19." (PMID 34636722, 2021). "Eosinophils from COVID-19 had decreased expression of the markers of the eosinophil lineage (CD15, CD66b, and CD193) and higher expression of classical activation markers, such as CD62L, CD69, and CD147." (PMID 34548411, 2021). "Similarly, the frequency of CD69 was lower on PD1−LAG-3− and PD1−TIM-3− CD8+ and CD4+ T cells compared to the expression on double-positive T cells in COVID-19 and malaria patients." (PMID 32983106, 2020). "We found that all ILC subsets in COVID-19 patients displayed a significantly higher frequency of CD69-expressing-cells compared with healthy controls, accompanied by a decreased frequency of cells expressing CD62L, as was previously noted for ILC2 and ILCps in COVID-19 patients." (PMID 39026668, 2024).
COVID-19 (continued). "In brief, the scRNA-seq followed by the immune transcriptomic analysis indicated an activation state (through CD69 and HLA class II genes), chemotaxis (e.g., CCL3 and CCL4), an inflammatory state (e.g., NFKBIA, PIK3R1, S100A9, etc.)in T cells, especially in CD8+T cells, in COVID-19 cases." (PMID 33717140, 2021). "Despite their CD69 expression, activated eosinophils from severe COVID-19 patients displayed lower CD11a, CD66b, and CD147 expression compared to CD69+ eosinophils from the group with moderate disease, suggesting a partial functional impairment of eosinophils in the more severe COVID-19 stages." (PMID 34548411, 2021). "Indeed, despite the strong eosinopenia, the absolute counts of CD69+ eosinophils were not significantly altered in COVID-19 patients." (PMID 34548411, 2021). "In addition, despite their CD69 expression, activated eosinophils in severe COVID-19 patients displayed lower levels of CD11a, CD63, and CD66b compared to the CD69+ eosinophils from patients with moderate COVID-19." (PMID 34548411, 2021). "Therefore, we shortlisted 18 (12 studies for COVID-19 convalescent subjects and 8 studies for vaccinated subjects) research articles containing 89 different datasets in which OX40 and CD137, CD69 and CD137 were used to measure spike-specific CD4+ and CD8 + T cells response respectively." (PMID 38167915, 2024). "In another study, however, CD69 expression of MAIT cells was reported to be higher in individuals with COVID-19 with early as opposed to late hospital discharge, highlighting the possibility that, in some instances, MAIT cells may have a protective role in individuals with milder disease." (PMID 33763658, 2021). "Despite this, the functionality of these T cells (Ki-67+, IFN-γ+, CD69+, CD38+ etc.)did not decrease with culture in UN or COVID-19+." (PMID 40698364, 2025). "We found a similar result for CD69+ cells in both CD4 and CD8 lymphocytes in pregnant and nonpregnant COVID-19 patients." (PMID 35901034, 2022). "There were reduced frequency and an activated phenotype of circulating MAIT cells in COVID-19 patients regardless of disease severity, as demonstrated by high levels of IL-17A, TNF-α, CD38, CD69, and HLA-DR expression." (PMID 36034704, 2022). "Further, we detected the phenotype of CD3+CD56+ NKT-like cells and found that the expression of activating receptor CD69, increased remarkably on NKT-like cells of pregnant women with COVID-19 compared with PHC group, non-pregnant women infected was also significantly higher than that in HC group." (PMID 39113896, 2024). "CD69 and PD1 expressing Vδ2+ T cells showed a higher level in severe patients compared to HDs, while CD69 expressing Vδ1 T cells but not PD1+ Vδ1 showed no significant change in severe patients compared with non-COVID-19 critically ill controls." (PMID 35159352, 2022). "In a cohort of 43 COVID-19 patients and 25 healthy controls, circulating MAIT cells displayed reduced frequency and an activated phenotype in individuals with COVID-19, regardless of disease severity, as characterised by high expression of IL-17A, TNFα, CD38, CD69 and HLA-DR." (PMID 34050887, 2022).
melanoma (65 papers, 2010 to 2026). A malignant, usually aggressive tumor composed of atypical, neoplastic melanocytes. "B-CD69 subtypes highly express CD69, and a single-cell RNA sequencing study of melanoma tissues revealed that CD69 + B cells were associated with the tumor response to immune checkpoint inhibitors." (PMID 38216927, 2024). "Increased numbers of CD69+CD103+ tumor-resident CD8+ T cells were associated with improved melanoma-specific survival in immunotherapy-naïve melanoma patients." (PMID 33854972, 2021). "In vitro, CCNB1 knockdown in melanoma cells augmented NK-92MI activation, as evidenced by increased expression of CD69, CD107a, IFN-γ, and NKG2D, thereby improving NK cell-mediated cytotoxicity." (PMID 40430484, 2025). "Large numbers of CD8+CD103+CD69+ TRM cells have been observed in human melanoma-infiltrated lymph nodes through both immunofluorescence and transcriptional analysis, and these cells were found to concentrate at the tumor border." (PMID 40862776, 2025). "Despite the differences in tumor outgrowth and LN metastasis exhibited by these tumors, we observed equivalent upregulation of the early activation marker CD69 on OT‐I cells in response to both melanomas at all stages of tumor progression analyzed." (PMID 39930625, 2025). "In lung cancer and melanoma, CLEC2C/CD69 can be used to predict response to PD-1/PD-L1 blocking cancer immunotherapy." (PMID 39553729, 2024). "CD8+ epidermal CD69+CD103+ TRM cells correlated with spontaneous disease control after inoculation with melanoma cells." (PMID 38562921, 2024). "Unexpectedly, co-culture with melanoma cells A375, 624mel and 888mel induced CD69 expression, suggesting that the stimulating ligand is shared between some cancers." (PMID 38321065, 2024). "Other changes observed in melanoma-bearing sentinel LN include (i) reduced CD69+CD8+T cell/Treg cell ratio, (ii) high PD-1 expression on CD4+T and CD8+T cells, and (iii) high CTLA-4 expression on γδ T cells." (PMID 38065972, 2023). "For example, in melanoma patients, the expression of CD69 on memory CD8T cells in tumor antigen-specific tissues can prevent the growth and spread of cancer cells by promoting immune homeostasis." (PMID 37880277, 2023). "Owing to the synergy of CXCL9 and αPD-L1, the number of CD69-positive CD8+ T cells in NPTyr-C9AP-treated melanoma reached 2.33 × 105 cells per gram tumor, which was 5.1- and 2.1-fold that in the NPTyr-CXCL9 and NPTyr-αPD-L1 groups, respectively." (PMID 37031188, 2023). "A subset of tumor-infiltrating lymphocytes (TIL) with several properties in common with TRM, including the expression of the CD103 integrin and CD69, has recently been identified in human tumors, including ovarian, lung and breast tumors, and melanoma." (PMID 37545498, 2023). "CD69 is significantly related to the tumor immune microenvironment and participates in the tumor immune infiltration process in melanoma." (PMID 36032150, 2022). "We found that the SP CD69+CD103- cells formed the largest group of CD8+ T cells in primary melanoma (DN mean = 28.78%, SP mean = 49.53%, DP mean = 19.64%), with the proportion of SP being significantly higher than that of DP (p=0.0088)." (PMID 36003398, 2022). "It was described, for example, that melanoma responders to antiPD-1 therapy had significantly increased numbers of CD69+ NK cells." (PMID 35329826, 2022). "It has previously been demonstrated that a population of CD56dimCD57+CD69+CCR7+KIR+ NK cells are expanded in tumour infiltrated lymph nodes of patients with melanoma, and that these NK cells are key effectors of anti-tumoral cytotoxicity." (PMID 35835762, 2022). "Here, analysis of CTR-DB data showed that CD69 is upregulated in lung cancer and melanoma patients who respond to PD-1/PD-L1 blockade, highlighting its potential as a predictor of pan-cancer response to anti-PD-1/PD-L1 immunotherapy." (PMID 36045683, 2022).